FGFR1 (fibroblast growth factor receptor 1)
Diseases named in the same sentence as FGFR1 in open-access papers (continued):
Sharing a sentence is not in itself a finding about the gene and the disease.
lymphoid neoplasm (continued). "While these reports revealed it is not uncommon for PDGFRA and FGFR1 genetically rearranged cells to differentiate into lymphoid neoplasms, hematologic diseases bearing PDGFRB mutations are rare." (PMID 22356850, 2012). "Similarly, microdeletions of FGFR1 have been identified in myeloid and lymphoid neoplasms." (PMID 40393028, 2025). "Furthermore, futibatinib has demonstrated clinical efficacy in patients harboring FGFR2-fusion-driven cholangiocarcinoma, and is in clinical trials to assess its efficacy in the treatment of solid or myeloid and lymphoid neoplasms with FGFR1 re-arrangements (NCT04189445)." (PMID 35574218, 2022). "Primary eosinophilic disorders are rare in the pediatric population and include chronic eosinophilic leukemia; myeloid/lymphoid neoplasms with rearrangements of PDGFRA, PDGFRB, FGFR1, or PCM1-JAK2; and idiopathic hypereosinophilic syndrome." (PMID 41552084, 2025). "Erdafitinib and pemigatinib, two TKIs targeting FGFR1-4 and FGFR1-3 respectively, obtained FDA approval for treating advanced urothelial cancer with FGFR2/3 genetic alterations and myeloid/lymphoid neoplasms with FGFR1 rearrangement." (PMID 39780187, 2025). "Myeloid or lymphoid neoplasms with eosinophilia can demonstrate gene rearrangements in PDGFRA, PDGFRB, FGFR1, JAK2, or FLT3 or ETV6::ABL or other tyrosine kinase gene fusion (MLN-TK)." (PMID 38611061, 2024). "The FGFR-tyrosine kinase inhibitor (TKI) pemigatinib has been introduced in the treatment of advanced cholangiocarcinoma and more recently for relapsed or refractory myeloid/lymphoid neoplasms with FGFR2 and FGFR1 rearrangements, respectively." (PMID 37715207, 2023). "We present the case of a male adult patient diagnosed with myeloid/lymphoid neoplasm with eosinophilia and BCR::FGFR1 rearrangement with transformation to cortical T-lymphoblastic lymphoma and erythroid precursors." (PMID 36698221, 2023). "In addition, humanized mice subcutaneously transplanted with KG1 could significantly inhibit the growth of tumors by oral administration of pemigatinib, and phase II clinical trials have been carried out in FGFR1 rearranged myeloid/lymphoid tumors (FIGHT, NCT03011372)." (PMID 36408177, 2022). "In August 2019, pemigatinib was recognized as an orphan drug in the US to treat myeloid/lymphoid tumors with eosinophilia, PDGFRA, PDGFRB, FGFR1 rearrangement, or PCM1-JAK2." (PMID 36408177, 2022). "Crucial differential diagnoses of Ph− MPN are the category of myeloid/lymphoid neoplasms with eosinophilia and gene rearrangement of PDGFRA, PDGFRB or FGFR1, or with PCM1-JAK2, and myelodysplastic/myeloproliferative neoplasms (MDS/MPN)." (PMID 34298741, 2021). "Mastocytoses were also listed within the spectrum of MPNs, while myeloid/lymphoid neoplasms with PDGFRA, PDGFRB, and FGFR1 rearrangements were considered separately." (PMID 34830822, 2021). "Among the alterations found in primary Eosinophilia, gene fusions involving PDGFRα, PDGFRβ, FGFR1 or JAK2 represent the biomarkers of WHO-defined "myeloid and lymphoid neoplasms with eosinophilia"." (PMID 34772467, 2021). "Fibroblast growth factor receptor 1 (FGFR1) micro deletions have been reported in myeloid and lymphoid neoplasms." (PMID 26768750, 2016). "Previously it has been found that mast cells harbor PDGFRA rearrangements in cases of myeloid and lymphoid neoplasms with eosinophilia and abnormalities in PDFGRA, PDGFRB, or FGFR1." (PMID 27648315, 2016). "A separate category has been made for myeloid and lymphoid neoplasms with eosinophilia and abnormalities of PDGFRA, PDGFRB, or FGFR1." (PMID 24764730, 2014). "In 2008 WHO classification, a new class of hematopoietic diseases, myeloid and lymphoid neoplasms with eosinophilia and abnormalities in PDGFRA, PDGFRB and FGFR1 genes, were introduced." (PMID 22356850, 2012). "In 2008, a new class of hematopoietic system disorders, myeloid and lymphoid neoplasms with eosinophilia and abnormalities in PDGFRA, PDGFRB and FGFR1 genes, was created by WHO." (PMID 22356850, 2012).
lymphoid neoplasm (continued). "Myeloid/lymphoid neoplasm with eosinophilia was excluded due to the absence of eosinophilia and lack of mutations in PDGFRA, PDGFRB, FGFR1, or PCM1-JAK2 gene rearrangement." (PMID 35228982, 2022). "Among them, FGFR1‐translocated myeloid and lymphoid neoplasms are the most frequently reported, for example, TFG‐FGFR1, BCR‐FGFR1, CNTRL‐FGFR1, ZNF198:FGFR1/ZMYM2‐FGFR1, CEP110‐FGFR1 and FGFR1OP2‐FGFR1 and even achieved complete remission in some patients when treated by FGFR inhibitor." (PMID 33655556, 2021). "Therefore, this disease belongs to the new WHO category of myeloid and lymphoid neoplasms with abnormalities in PDGFRA, PDGFRB and FGFR1 genes." (PMID 22356850, 2012). "Clonal eosinophilia is associated with myeloid or lymphoid neoplasms harboring PDGFRA, PDGFRB, or FGFR1 rearrangements, Philadelphia-negative myeloproliferative neoplasms, acute myeloid leukaemia, and B- or T-lymphoblastic leukemia/lymphoma featuring marked eosinophilia." (PMID 41552084, 2025). "Leukemias harboring FGFR1 fusions have previously been referred to as 8p11.2 myeloproliferative syndrome (EMS) or stem cell leukemia/lymphoma (SCLL) and are currently referred to as Myeloid/lymphoid neoplasms with FGFR1 rearrangement based on the most recent WHO classification system." (PMID 40881645, 2025).
bladder cancer (59 papers, 2010 to 2026). "These existing literature and our findings highly support the association of FGFR1 with NB characteristics and neuronal differentiation of bladder cancer." (PMID 35068946, 2021). "Switching of FGFR expression to the IIIc isotypes has been shown for FGFR2 and FGFR1, and was described to be associated with tumour progression in prostate and bladder cancer." (PMID 20234367, 2010). "Hence, we systematically screened a cohort of squamous differentiated specimens and publically available datasets of “squamous-like” bladder cancers for expression, amplification, mutation and chromosomal rearrangement of FGFRs (FGFR1-3), in order to evaluate putative pathway activation." (PMID 27669755, 2016). "Recent studies have reported the role of the TTYH3/MK5 axis in regulating GSK‐3β/β‐catenin signaling in hepatocellular carcinoma, and its involvement in bladder cancer progression through the FGFR1/H‐Ras/A‐Raf/MEK/ERK pathway." (PMID 38827027, 2024). "FGFR1 is the most commonly altered FGFR in human cancers but studies on FGFR1 in bladder cancer are very few." (PMID 39031286, 2024). "For example, TTYH3 has been shown to facilitate bladder cancer through the FGFR1/H‐Ras/A‐Raf/MEK/ERK pathway, and its upregulation promotes EMT in cholangiocarcinoma." (PMID 38827027, 2024). "Recently FDA-approved, erdafitinib, a pan-FGFR (FGFR1-4) tyrosine kinase inhibitor (TKI), has shown efficacy in treating advanced bladder cancer and intermediate- and high-risk NMIBC by blocking tyrosine kinase signaling." (PMID 39410541, 2024). "In bladder cancer, FGFR1 and FGFR3 alterations are commonly found and they have been implicated in the pathogenesis of UBC." (PMID 39031286, 2024). "Some alterations are more frequently observed in certain cancers, for example, FGFR3 mutations or translocations in bladder cancer, FGFR2 fusions or rearrangements in cholangiocarcinoma, and FGFR1 rearrangements in myeloid/lymphoid neoplasms." (PMID 37000035, 2023). "Various somatic mutations of FGFR family members also lead to carcinogenesis, such as mutations in FGFR1 sequence in lung tumors and gliomas, FGFR2 in carcinomas, and FGFR3 in bladder carcinomas and multiple myelomas." (PMID 38282676, 2023). "First, although many types of MAPK signaling regulate cancer properties, this study focused on the mechanism of the H-Ras/MEK/ERK pathway and FGFR1 phosphorylation in bladder cancer." (PMID 36142409, 2022). "The collective findings indicate that bladder cancer cells are regulated by TTYH3 through FGFR1 and the H-Ras/A-Raf/MEK/ERK pathways." (PMID 36142409, 2022). "The proliferation, migration, and invasion of bladder cancer cells are regulated by FGFR1 and MAPK signaling." (PMID 36142409, 2022). "FGFR1 is a cell surface receptor overexpressed by several tumors, including breast, lung, ovarian, head and neck and bladder cancers and constitutes an attractive tumor marker for development of targeted therapeutics." (PMID 34635096, 2021). "Our analysis revealed that the expression status of FGFR1, which is highly enriched in ‘stromal-rich’ subgroup in consensus classification of bladder cancer, mainly separates the NB group from the two other groups." (PMID 35068946, 2021). "As FGFR1 is the main player characterizing this group, we checked the enrichment of FGFR1 regulon activity in each consensus subgroup of primary bladder cancer." (PMID 35068946, 2021). "In literature, FGFR1 has been shown be expressed at higher levels in bladder cancers showing mesenchymal features." (PMID 35068946, 2021). "Further FGFR1 expression was high in most small cell carcinoma of the bladder, which is a rare type of bladder cancer with neuroendocrine differentiation." (PMID 35068946, 2021). "In this particular subtype, the prognosis of bladder cancer can be independently evaluated by a risk model composed of EMP1, FGFR1, and CAVIN1 genes." (PMID 32695477, 2020).
bladder cancer (continued). "CASC8 is also involved in the regulation of the glycolysis in bladder cancer cells through modulating expression of the fibroblast growth factor receptor 1 (FGFR1)." (PMID 33123468, 2020). "High positive FGFR1 or 3 expression ratios were predicted in cholangiocarcinoma (58%), followed by bladder cancer (42%), endometrial carcinoma (35%), and ovarian cancer (34%)." (PMID 32596330, 2020). "Rogaratinib (BAY1163877) is a selective oral inhibitor of FGFR1-4; promising results have been reported from a phase I expansion cohort in advanced bladder cancer patients prescreened for FGFR1 or 3 mRNA expression levels by RNA-ISH (NCT01976741)." (PMID 32596330, 2020). "Its overexpression was shown to significantly suppressed bladder cancer cell proliferation by reducing the glycolysis of bladder cancer cells and interacting with fibroblast growth factor receptor 1 (FGFR1)." (PMID 32765426, 2020). "Fusion oncogenes containing parts of FGFR1–3 and a number of different partners were found in smaller percentages of patients with glioblastoma, bladder cancer, and a number of additional malignancies." (PMID 31527449, 2019). "The enhancement of the FGFR2 pathway would lead to urothelium proliferation and FGFR1, as well as FGFR3 gene amplification can cause urinary bladder carcinoma." (PMID 31878098, 2019). "FGFR1 amplifications have also been reported in oral squamous cell carcinoma, ovarian cancer, bladder cancer and rhabdomyosarcoma." (PMID 28030802, 2017). "In bladder cancer, we additionally found fibroblast growth factor receptor 1 (FGFR1) and its downstream regulatory subunits of the protein phosphatase 2 (PP2; inhibitor of cell growth and division), and the pro-proliferative inhibitor of PP2, KIAA1524 (CIP2A)." (PMID 28775339, 2017). "Our simulation results suggest that when E2F1, TGFBR1, and FGFR1 are simultaneously active, bladder cancer cells become highly invasive (EMT = 3)." (PMID 28775339, 2017). "In contrast, aberration of FGFR1 is a frequent event in bladder cancer contributing to rapid disease progression." (PMID 28775339, 2017). "A distinct pattern of cancer mutations in FGFR1-4 can reflect differences in cancer types and their etiology, with FGFR3 mutations being most prevalent in a single cancer type (i.e bladder cancer)." (PMID 26992226, 2016). "As previously reported, FGFR1 is highly expressed in various malignancies and its overexpression induces a series of cellular and molecular changes associated with EMT in bladder cancer and PCa." (PMID 26451614, 2015). "Our recent data, however, show that activation of overexpressed FGFR1 in bladder cancer cell lines is sufficient to induce an epithelial mesenchymal transition (EMT)." (PMID 22899908, 2012). "All three compounds were found to be cytotoxic and/or cytostatic on a range of FGFR3- or FGFR1-dependent bladder cancer cell lines in vitro and to reduce FGFR phosphorylation and downstream signalling, with PD173074 and TKI258 showing the greatest effect." (PMID 22899908, 2012). "We have demonstrated that FGFR1 expression is increased in bladder cancer and that activation of FGFR1 induces an EMT in urothelial carcinoma (UC) cell lines." (PMID 22701738, 2012). "For example, the database BoostDM only covers FGFR3 based on mutational data from bladder cancer and provides no information at all for FGFR1, FGFR2 or FGFR4." (PMID 41361008, 2026). "Although we complemented the JMSU1-based system with J82-RS cells as an independent FGFR1-expressing resistant model, further validation using additional FGFR1-dependent bladder cancer models, such as UMUC3, would strengthen the generalizability of our findings." (PMID 41315241, 2025). "A FGFR1-NTM fusion can be found in bladder cancer, and fusion was described in NSCLC a BAG4-FGFR1." (PMID 35955806, 2022). "Targeting FGFR1 in less-differentiated bladder cancer subgroups may sensitize tumors for adopted treatments or subsequent chemotherapy." (PMID 35887247, 2022).
bladder cancer (continued). "The extensively amplified hot zones on the p of chromosome 8 may be associated with FGFR1 and IKBKB, which are often deregulated by amplification in lung, colon, and bladder cancers." (PMID 34054918, 2021). "Overexpression of CASC8 through interacting with FGFR1 and inhibiting FGFR1-mediated LDHA phosphorylation could suppress glycolysis in bladder cancer cell." (PMID 33123468, 2020). "Our findings are consistent with the results of the TCGA data set for the “squamous-like” subtype of bladder cancer (n = 85), which revealed reduced overall expression of FGFR1 and FGFR2 in tumors compared to normal tissue, while expression of FGFR3 remained high." (PMID 27669755, 2016). "The role of fibroblast growth factor receptors 1 and 3 (FGFR1/3) was described in bladder cancer." (PMID 27529216, 2016). "Thus,FGFR1 is expressed by the mesenchymal subset of bladder cancer cells suggesting that the tumour EMT phenotype is an important determinant for the biological effects of FGFR inhibitors in patients." (PMID 27711186, 2016). "Recent work has shown that fibroblast growth factor receptor-1 (FGFR1) promotes invasion of bladder cancer cells expressing ZEB1, a marker of epithelial-mesenchymal transition (EMT); FGFR inhibition in this study reduced metastatic spread of orthotopically implanted bladder cancer cells." (PMID 24312263, 2013). "More, recently it has been shown that FGFR1 is overexpressed in bladder cancer." (PMID 22899908, 2012). "Whether cAMP levels influence FGFR1-induced phenotypes in human bladder cancer cell lines needs to be investigated." (PMID 22701738, 2012). "Additionally, it was indicated that FGFR1 could play a crucial role in invasion and metastasis, but its role in driving bladder cancer cell proliferation might be less important than FGFR3." (PMID 39031286, 2024). "For tumors not responding to standard chemotherapy as defined by overexpression of stromal signatures and FGFR1 target gene expression, the inhibition of FGFR activities by targeted approaches may be superior to predispose muscle-invasive bladder cancer to subsequent immune oncology treatment." (PMID 35887247, 2022). "In addition, we found FGFR1 only in the regulatory core of bladder cancer." (PMID 28775339, 2017). "Although FGFR3 alterations are common in early-stage bladder cancer, particularly in NMIBC, a distinct subset of MIBC displays FGFR1 amplification or overexpression." (PMID 41315241, 2025). "CASC8 protein binds to the fibroblast growth factor receptor 1 (FGFR1) and abrogates lactate dehydrogenase-A phosphorylation, thereby reducing glycolysis, and inhibiting bladder cancer cell growth." (PMID 38544804, 2024). "In bladder cancer, tweety family member 3 inhibits phosphorylation of FGFR1 and downregulates the H‐Ras/A‐Raf/MEK/ERK signaling pathway (downstream targets include c‐Jun and c‐Fos) to inhibit the invasion and migration of bladder cancer cells." (PMID 37750089, 2023). "As amplification/overexpression of FGFR1, FGFR2, and FGFR3 contributes to progression of lung, gastric, and bladder cancers, respectively, we verified their level of expression in all analyzed cell lines." (PMID 33898310, 2021). "In our previous study, MPT0L145 arrested cell proliferation through inhibition of the phosphorylation of FGFR1 and FGFR3 in bladder cancer cells." (PMID 34885226, 2021). "Two non‐selective FGFR1–3 inhibitors, erdafitinib (JNJ‐42756493) and pemigatinib (INCB054828) have been approved and are being marketed to treat bladder cancer and cholangiocarcinoma in patients with FGFR2 or FGFR3 rearrangements." (PMID 34114373, 2021). "Among the six identified survival-related genes, three-genes, EMP1, FGFR1, and CAVIN1, were identified as potential independent prognostic markers for the specific bladder cancer subtype with clinical features described." (PMID 32695477, 2020).
bladder cancer (continued). "In bladder cancer cells, FGFR3 expression directly correlates with an epithelial-like state whereas FGFR1 expression correlates with a more mesenchymal-like state." (PMID 25596738, 2015). "In contrast to FGFR3 and FGFR1, FGFR2 appears to have a protective or tumour-suppressor role in bladder cancer." (PMID 22899908, 2012). "The findings indicate that the expression of TTYH3 may affect the phosphorylation of FGFR1, inhibit H-Ras/A-Raf/MEK signaling, and inhibit the proliferation of bladder cancer cells." (PMID 36142409, 2022). "Based on all these information, we checked the expression of CXCL16, T cell chemoattractant in bladder cancer cell lines and identified a significant negative correlation with FGFR1 expression." (PMID 35068946, 2021). "The strongest negative correlation (rho = 0.83) was between FGFR1 and FGFR3 in bladder carcinoma." (PMID 29322935, 2017). "FGFR fusions with oncogenic activity have been previously identified in bladder cancer (FGFR3), lymphoma (FGFR1 and FGFR3), acute myeloid leukemia (FGFR1), multiple myeloma, myeloproliferative neoplasms, and most recently glioblastoma multiforme (FGFR1 and FGFR3)." (PMID 24550739, 2014). "Therefore, although the expression of FGFR1 was higher than that of FGFR3 in the present study, the authors reaffirmed the important role of FGFR3 in the development and progression of bladder cancer, and our results are consistent with those of previous reports." (PMID 41228379, 2025). "Some studies have focused on activating FGFR1 and FGFR3 in bladder cancer; however, other FGFRs and FGF-ligands were not studied." (PMID 31369573, 2019).